SLCO1B3-SLCO1B7 (SLCO1B3-SLCO1B7 readthrough)
Description:
Mediates the Na(+)-independent uptake of organic anions. Transports the conjugated steroids 17-beta-glucuronosyl estradiol (17beta-estradiol 17-O-(beta-D-glucuronate) or E2G) and dehydroepiandrosterone 3-sulfate (DHEAS) at the smooth endoplasmic reticulum membrane (SER), granting access to metabolizing enzymes. Contributes to the metabolism of bile acids such as taurocholate (cholyltaurine) and lithocholate, by functioning as a doorway between SER and cytosol, thereby decreasing their circulating levels and protecting the organism from their detergent properties. Regulates access or exit of drugs to the SER lumen.
Synonyms: LST-3TM12; OATP1B3-1B7
Tractability: Antibody: UniProt places it where antibodies can reach, with high confidence; UniProt predicts a signal peptide or a membrane-spanning region; its Gene Ontology location is reachable by antibodies, with medium confidence.
Gene: Protein-coding gene on chromosome 12 (20,815,674 to 21,090,245, forward strand). Ensembl gene ENSG00000257046.
Subcellular location: Smooth endoplasmic reticulum membrane; Cell membrane; Endoplasmic reticulum membrane
Gene Ontology:
Molecular function: bile acid transmembrane transporter activity; secondary active transmembrane transporter activity; transmembrane transporter activity
Biological process: bile acid and bile salt transport; sodium-independent organic anion transport; transmembrane transport
Cellular component: basolateral plasma membrane; endoplasmic reticulum membrane; membrane; plasma membrane; smooth endoplasmic reticulum membrane
Genetic constraint (gnomAD): Loss-of-function variants: 30 observed, 33.17 expected, observed/expected ratio (o/e) 0.9, 90% interval 0.68 to 1.23. The upper end of that interval is the gene's LOEUF score, 1.23, which puts it in group 5 of 6, group 1 being the genes least tolerant of losing a copy. Missense variants: 562 observed, 489.24 expected, observed/expected ratio (o/e) 1.15, 90% interval 1.07 to 1.23. Synonymous variants: 188 observed, 169.56 expected, observed/expected ratio (o/e) 1.11, 90% interval 0.98 to 1.25.